SMARCA5 (SNF2 related chromatin remodeling ATPase 5)
Diseases named in the same sentence as SMARCA5 in open-access papers (continued):
Sharing a sentence is not in itself a finding about the gene and the disease.
ovarian carcinoma (6 papers, 2021 to 2024). A malignant neoplasm originating from the surface ovarian epithelium. "We have successfully demonstrated the potential of the novel SMARCA5/CHD4 inhibitor ED2-AD10 in combination with cisplatin for the first time in ovarian cancer cells." (PMID 34161330, 2021). "We have also successfully demonstrated the potential of the combination therapy of platinum agents and CHD4 inhibitor by introducing the first-in-class SMARCA5/CHD4 inhibitor ED2-AD101 in ovarian cancer cells." (PMID 34161330, 2021). "In ovarian cancer, the interplay between Rsf-1 and SMARCA5 contributes to tumor cell survival and growth." (PMID 34736517, 2021). "The SMARCA5 inhibitor ED2-AD101 was applied to modulate SMARCA5 activity in ovarian cancer cells." (PMID 39500888, 2024).
bladder cancer (5 papers, 2014 to 2022). "In this context, miR-100 should act as an oncomiR because the downregulation of SMARCA5 could result in deficiencies in DNA repair that could promote chromosomal instability, a hallmark of high-grade bladder cancer." (PMID 25493074, 2014).
glioma (5 papers, 2020 to 2024). A benign or malignant brain and spinal cord tumor that arises from glial cells (astrocytes, oligodendrocytes, ependymal cells). "Survival curves for gliomas showed that the survival rates among patients exhibiting high SMARCA5 expression were much poorer than among those expressing low SMARCA5 levels." (PMID 32632040, 2020). "SMARCA5, which is highly expressed in high-grade gliomas, was a direct downstream target of miR-146b-5p in the GSC/MSC fusion cells." (PMID 32632040, 2020). "To date, several circRNAs have been reported to play crucial roles in gliomas, such as circ-SMARCA5, circ-MMP9, circ-NT5E, circ-TTBK2, and circ-LINC-PINT." (PMID 31905344, 2020). "Collectively, these findings demonstrate that miR-146b-5p suppresses the malignant phenotype of GSC/MSC fusion cells in the glioma microenvironment by targeting a SMARCA5-regulated TGF-β pathway." (PMID 32632040, 2020). "In addition, analysis of SMARCA5 expression in gliomas with different WHO grades showed that, consistent with the TCGA data, SMARCA5 expression in high-grade gliomas was marked higher than in low-grade gliomas and normal tissue." (PMID 32632040, 2020). "In our experiments, we confirmed the role of a miR-146b-5p/SMARCA5/TGF-β axis in malignant F-GSC/MSCs in the glioma microenvironment, which may be a potential therapeutic target for treatment of glioma in the future." (PMID 32632040, 2020).
hepatocellular carcinoma (4 papers, 2019 to 2025). A malignant tumor that arises from hepatocytes. "Another research reveals that Circ-SMARCA5 level is reduced in hepatocellular carcinoma (HCC) tissues compared with adjacent tissues and its low expression is correlated with poor clinicopathological features in HCC patients." (PMID 31601173, 2019).
lung carcinoma (4 papers, 2020 to 2025). "This is the first study to show an inverse association between nm23‐H1 and miR‐660‐5p, and confirm that nm23‐H1 inhibits tumor progression and bone‐specific metastasis of lung cancer by regulating miR‐660‐5p/SMARCA5/RANKL axis." (PMID 32022430, 2020). "The RANKL expression induced by miR‐660‐5p was reversed as a result of SMARCA5 knockdown, indicating that miR‐660‐5p could play a role in bone‐specific metastasis of lung cancer cells by modulating RANKL signaling through targeting SMARCA5." (PMID 32022430, 2020). "Overexpression of SMARCA5 suppressed lung cancer cell migration and invasion." (PMID 32022430, 2020). "Moreover, miR‐660‐5p influences the proliferation, migration, invasion, and bone‐specific metastasis of human lung cancer cells through the miR‐660‐5p/SMARCA5/RANKL signaling pathways." (PMID 32022430, 2020). "Overexpression of SMARCA5 suppressed the L9981‐BoM cell invasion and migration, indicating that SMARCA5 could be involved in the regulation of tumor progression in bone‐specific metastatic lung cancer cells." (PMID 32022430, 2020). "miR-660 could inhibit lung cancer progression and bone metastasis by regulating SMARCA5 expression." (PMID 37107669, 2023). "In addition, as the potential target gene of miR‐660‐5p, SMARCA5 overexpression in vitro suppressed tumor progression and osteolytic metastasis associated RANKL signaling, which is congruent with the effect of nm23‐H1 on the lung cancer cells." (PMID 32022430, 2020). "Furthermore, we investigated whether SMARCA5 contributed to the migration and invasion of bone‐specific metastatic lung cancer cells." (PMID 32022430, 2020). "Collectively, these results show that miR‐660‐5p directly inhibits SMARCA5 expression by targeting its 3'UTR and also induces RANKL signaling of lung cancer cells." (PMID 32022430, 2020). "We further investigated whether miR-660-5p promoted proliferation and metastasis of lung cancer cells via LIMCH1, SMARCA5, and TPP2." (PMID 38057344, 2023). "Nm23‐H1 inhibits tumor progression and bone‐specific metastasis of lung cancer by regulating miR‐660‐5p/SMARCA5/RANKL axis, which indicates the related genes may serve as potential targets for the treatment of human lung cancer." (PMID 32022430, 2020).
multiple myeloma (3 papers, 2019 to 2025). "We aimed to investigate the correlation of Circ-SMARCA5 with disease severity and prognosis in multiple myeloma (MM), and its underlying mechanisms in regulating cell proliferation and apoptosis." (PMID 31601173, 2019). "For example, circ‐SMARCA5 can target miR‐767‐5p to inhibit the progression of multiple myeloma, and hsa_circ_0002483 can target miR‐182‐5p to inhibit the progression of non‐small‐cell lung cancer." (PMID 37324880, 2023).
Anxiety (2 papers, 2019 to 2024). Intense feelings of nervousness, tension, or panic often arise in response to interpersonal stresses. "First studies in that respect have suggested a role for aberrant regulation of CHD-type chromatin remodeling factors in learning and memory as well as contextual fear extinction in particular, or of the ISWI-related remodeling enzyme SNF2H (also known as SMARCA5) in high anxiety behavior (HAB) mice." (PMID 36946487, 2024).
bladder urothelial cancer (2 papers, 2014 to 2022). "In this study, we predict that SMARCA5 may be potential biomarker of bladder urothelial cancer; however, this needs validation." (PMID 36186429, 2022). "It is reasonable to think that the down expression of miR-100 that we previously observed in low-grade, non-invasive bladder urothelial cancer is related to the lack of control of mTOR and FGFR3 and to the maintenance of genomic stability due to not interfering with SMARCA5." (PMID 25493074, 2014).
breast tumor (2 papers, 2011 to 2020). "Consistently, the protein of SMARCA5 was high expressed in breast tumor samples as compared with the corresponding controls." (PMID 32838810, 2020).
colon cancer (2 papers, 2017 to 2023). "In colon cancer circ-SMARCA5 sponge miR-552, where upregulation of miR-552 partially prevented colon cancer cells from growing and invading." (PMID 37587156, 2023). "As compared to control group, the expression of circ-NOL10, circ-LDLRAD3, circ-RHOT1, and CEA level in CRC, colon cancer, and rectum cancer patients was significantly upregulated (P ˂ 0.001, 0.001, 0.002), while circ-SMARCA5 was insignificantly upregulated (P = 0.233, 0.264, 0.280 respectively)." (PMID 37587156, 2023). "When SIRT1-Flag tagged expression plasmid was transfected into Human colon cancer HCT116 cell line, the acetylation levels of SMARCA5, MTA2, HMGA1, EGFR, CHD4 and GOT2 decreased as equal amounts of the proteins were immunoprecipitated." (PMID 28676654, 2017).
intrahepatic cholangiocarcinoma (2 papers, 2020 to 2025). A carcinoma that arises from the intrahepatic bile duct epithelium in any site of the intrahepatic biliary tree. "Circ_0003418 and circRNA_101505 are decreased in HCC tissues, while circ-SMARCA5 is reduced in intrahepatic cholangiocarcinoma (ICC)." (PMID 32171304, 2020).
medulloblastoma (2 papers, 2021). A malignant, invasive embryonal neoplasm arising from the cerebellum. "Dysregulation of GNP expansion can result in a hypoplastic cerebellum, as was observed for Smarca5 cKO mice, or conversely, cause some subtypes of medulloblastoma as shown for activating hedgehog (HH) mutations." (PMID 34295220, 2021). "The seven circRNAs, FKBP8, SMARCA5, GLIS1, BACH1, ZKSCAN1, CDYL, and OGDH, with a reduced expression in medulloblastoma versus cerebellum, while their corresponding linear mRNAs do not follow this change of expression pattern, were selected for further analysis." (PMID 34680287, 2021).
microcephaly (2 papers, 2023 to 2025). A congenital or acquired developmental disorder in which the circumference of the head is smaller than normal for the person's age and sex. "Indeed, the Smarca5 mouse models are representative of the phenotype in individuals with SMARCA5 germline pathogenic variants who present with developmental delay, short stature, and microcephaly." (PMID 37841849, 2023). "Like the human BPTF and SMARCA5 NDDs, microcephaly is a common feature of the forebrain-specific conditional knockout mice for the Smarca5 and Bptf genes." (PMID 37841849, 2023). "Since the ISWI subunits are interchangeable within the NURF complex, the severe microcephaly observed in Smarca5 and Bptf conditional knockouts also suggest that Smarca1 and Smarca5 may regulate brain growth via different mechanisms." (PMID 37841849, 2023).
asthma (1 paper, 2015). "SNPs in USP38 have been associated with susceptibility to asthma, but the gene lies in a 700-kb region close to malaria candidates in the GYP-E/A/B gene cluster as well as the SMARCA5 and FREM3 loci." (PMID 25805752, 2015).
Cerebellar hypoplasia (1 paper, 2025). Cerebellar hypoplasia is a descriptive term implying a cerebellum with a reduced volume, but a normal shape and is stable over time. "Additional genetic ablation experiments in vivo revealed that conditional deletion of Smarca5 in cerebellar granule cell neuron precursors (GCNPs), the cell origin of SHH-MB, significantly reduces the proliferative capacity of GCNPs and leads to cerebellar hypoplasia in mice." (PMID 40681754, 2025).
cerebellar tumors (1 paper, 2025). "Via immunohistochemistry we observed reduced SMARCA5 expression in cerebellar tumors of Math1-cre::Smarca5Fl/Fl::SmoM2Fl/+ mice, which displayed a significant decrease in proliferating tumor cells in the cerebellum at P5 as compared to control tumor mice." (PMID 40681754, 2025).
colon adenocarcinoma (1 paper, 2021). "Through analysis of TCGA database, the SMARCA5 and SMARCA1 gene have divergent patterns of expression in cancers, such as colon adenocarcinoma (COAD), LUAD and stomach adenocarcinoma (STAD), suggesting that they have differential roles or even opposing roles." (PMID 34736517, 2021).
depression (1 paper, 2020). "Given that the overexpression of BAZ1A and SMARCA5 together but not individually results in a susceptibility phenotype after subthreshold training, it is possible that the BAZ1A-SMARCA complex is instrumental in regulating the formation of depression-like behaviors." (PMID 32957495, 2020).
diabetes (1 paper, 2024). "Similarly, other studies have shown that in conditions of diabetes and obesity, the expression of SMARCA5, a member of the SWI/SNF family of proteins, is reduced in endothelial cells of the lungs and heart." (PMID 39519233, 2024).
lung adenocarcinoma (1 paper, 2021). A carcinoma that arises from the lung and is characterized by the presence of malignant glandular epithelial cells. "Taken together, further research is required on SMARCC1, SMARCC2, and SMARCA5, together with TOP1, as predictive biomarkers of resistance to geldanamycin derivatives as HSP90 inhibitors in lung adenocarcinoma." (PMID 33802597, 2021).
lymphoma (1 paper, 2020). A malignant (clonal) proliferation of B- lymphocytes or T- lymphocytes which involves the lymph nodes, bone marrow and/or extranodal sites. "Data from global CRISPR/Cas9 screen identified that SMARCA5 targeting was very efficient and caused cell growth inhibition in several additional AML cell lines (OCI-AML2, OCI-AML3) and also in lymphoma and carcinoma cell lines." (PMID 32197313, 2020).
Macrocephaly (1 paper, 2023). Occipitofrontal (head) circumference greater than 97th centile compared to appropriate, age matched, sex-matched normal standards. "Individuals with pathogenic variants in SMARCA1 are phenotypically distinct in comparison to BPTF and SMARCA5 NDDs, as suggested primarily by the high penetrance of macrocephaly." (PMID 37841849, 2023).
melanoma (1 paper, 2015). A malignant, usually aggressive tumor composed of atypical, neoplastic melanocytes. "We next interrogated transcriptome data to assess expression of the BPTF, SMARCA1 and SMARCA5 subunits of NURF in a collection of human melanoma cells." (PMID 26440048, 2015).
Nicolaides-Baraitser syndromes (1 paper, 2023). "Given that a clinical continuum is observed in Coffin-Siris and Nicolaides-Baraitser syndromes depending on which BAF encoding gene is mutated, it is not unusual to consider that SMARCA1, SMARCA5, and BPTF NDDs may also align along a clinical spectrum." (PMID 37841849, 2023).
prostate tumors (1 paper, 2024). "Clinically, USP3 levels are positively correlated with SMARCA5 in prostate tumors with high Gleason." (PMID 39500888, 2024).
Williams syndrome (1 paper, 2024). "Loss of function of the SMARCA5 can result in neurodevelopmental disorder and Williams syndrome." (PMID 39500888, 2024). "Loss of function of the SMARCA5 can cause neurodevelopmental disorder and Williams syndrome." (PMID 39500888, 2024).
tumor (33 papers, 2014 to 2025). "As compared to SMB21 parental cells, Smarca5 knockout significantly reduced cell proliferation, similar to loss of Smo, supporting our screen findings that Smarca5 is required for SHH-MB tumor cell growth." (PMID 40681754, 2025). "Except for these three genes, two genes, RAD18 and sMARCA5, linked to tumor progression and poor prognosis in several cancers were poorly studied in HCC." (PMID 39865406, 2025). "We also observed that higher expression of USP3 was positively associated with stronger expression of SMARCA5 in tumor tissues." (PMID 39500888, 2024). "Furthermore, loss of Smarca5 in GCNPs in an established mouse model of SHH-MB results in prolonged survival of tumor bearing mice." (PMID 40681754, 2025). "Interestingly, apoptotic activity in tumor areas was increased both in mice with a heterozygous as well as a homozygous loss of Smarca5 as compared to control tumor mice." (PMID 40681754, 2025). "While we had noticed insufficient recombination of the Smarca5 locus in a subset of tumor cells at early stages, we found that the fraction of SMARCA5-negative cells decreased during postnatal tumor development." (PMID 40681754, 2025). "USP3 knockdown inhibited tumor growth, while co-overexpression of SMARCA5 significantly rescued this effect." (PMID 39500888, 2024). "We found that GC patients with high DNA binding activities of SMARCA5 and E2F3 and high phosphorylation of CCNL1 (at T67) and SMC4 (at S41) in tumor tissues associated with poor prognoses (Log-rank test, p < 0.05)." (PMID 36788224, 2023). "In agreement with a potential role of chromatin remodeling in the prevention TRC-dependent DNA damage, SMARCA4-, SMARCA5- and INO80-deficient tumor samples display significantly increased R-loop mutation burden." (PMID 37898641, 2023). "We therefore investigated the epigenomic and phenotypic impact of controlled stepwise attenuation of Smarca5 function in the context of primary cell transformation, a process relevant to tumor formation." (PMID 35269430, 2022). "Functional assays using NSCLC cell lines suggest that it mediates the tumor suppressor activity of the circRNA SMARCA5 to inhibit tumor growth and induce apoptosis." (PMID 35406615, 2022). "In ICC, circ-SMARCA5 was found to be reduced in tumor compared to adjacent tissues, and the level of circ-SMARCA5 was found to be related to the chemotherapy sensitivity in ICC cells." (PMID 34526098, 2021). "In ICC, circRNA SMARCA5 was demonstrated to correlate with better clinical tumor features and prognosis and more sensitivity to chemotherapy." (PMID 34526098, 2021). "Exonic deletions were detected in the PPP2R5A, FHIT, LRP1B, and OPCML tumor suppressor genes, as well as in genes implicated in cellular proliferation (CCNB1, ANAPC5, PIK3C2A) and DNA repair (SMARCA5)." (PMID 30836646, 2019). "In that regard, we determined the efficacy of Smarca5 loss by quantifying the fraction of SMARCA5-negative cells to total tumor cells via immunostaining." (PMID 40681754, 2025). "CircSMARCA5 is a circRNA formed by its parental gene SMARCA5 via back splicing which is dysregulated in expression in a variety of tumors and is involved in tumor development with dual functions as an oncogene or tumor suppressor." (PMID 36231036, 2022). "Additionally, the expression level of circSMARCA5 is inevitably influenced by the transcription activity of its parent gene SMARCA5, which promotes the expression abundance of circSMARCA5 and therefore affects tumor development." (PMID 36231036, 2022). "Finally, it is worth highlighting that SMARCA5, which is overexpressed in different tumor types, forms a chromatin-remodeling complex with bromodomain adjacent to zinc finger domain 1B (BAZ1B) that facilitates the access of TOP1 at the replication fork." (PMID 33802597, 2021). "In addition, SMARCA5 expression reversed miR-146b-5p-mediated inhibition of tumor invasion and migration." (PMID 32632040, 2020).